CASR (calcium sensing receptor)
Description:
G protein-coupled receptor that senses changes in the extracellular concentration of calcium ions and plays a key role in maintaining calcium homeostasis. Senses fluctuations in the circulating calcium concentration: activated by elevated circulating calcium, leading to decreased parathyroid hormone (PTH) secretion in parathyroid glands (By similarity). In kidneys, acts as a key regulator of renal tubular calcium resorption (By similarity). Ligand binding causes a conformation change that triggers signaling via guanine nucleotide-binding proteins (G proteins) and modulates the activity of downstream effectors. CASR is coupled with different G(q)/G(11), G(i)/G(o)- or G(s)-classes of G proteins depending on the context. In the parathyroid and kidney, CASR signals through G(q)/G(11) and G(i)/G(o) G proteins: G(q)/G(11) coupling activates phospholipase C-beta, releasing diacylglycerol (DAG) and inositol 1,4,5-trisphosphate (IP3) second messengers, while G(i)/G(o) coupling mediates inhibition of adenylate cyclase activity. The G protein-coupled receptor activity is activated by a co-agonist mechanism: aromatic amino acids, such as Trp or Phe, act concertedly with divalent cations, such as calcium or magnesium, to achieve full receptor activation. Acts as an activator of the NLRP3 inflammasome via G(i)/G(o)-mediated signaling: down-regulation of cyclic AMP (cAMP) relieving NLRP3 inhibition by cAMP. Acts as a regulator of proton-sensing receptor GPR68 in a seesaw manner: CASR-mediated signaling inhibits GPR68 signaling in response to extracellular calcium, while GPR68 inhibits CASR in presence of extracellular protons (By similarity).
Synonyms: CaR; hCasR; PCaR1; GPRC2A; FHH; NSHPT; EIG8; FIH; HHC; HHC1; HYPOC1
Tractability: Small molecule: an approved drug acts on it; a structure with a bound ligand is known; a high-quality ligand is known; it belongs to a druggable protein family. Antibody: UniProt places it where antibodies can reach, with high confidence; its Gene Ontology location is reachable by antibodies, with high confidence; UniProt predicts a signal peptide or a membrane-spanning region. PROTAC: UniProt records ubiquitination sites on it; a small molecule that binds it is known. Other modalities: an approved drug acts on it.
Target class: Ion receptor (family C GPCR); Calcium sensing receptor; Family C G protein-coupled receptor; Membrane receptor
Gene: Protein-coding gene on chromosome 3 (122,183,668 to 122,291,629, forward strand). Ensembl gene ENSG00000036828.
Subcellular location: Cell membrane
Pathways (Reactome):
Signal Transduction: Class C/3 (Metabotropic glutamate/pheromone receptors); G alpha (i) signalling events; G alpha (q) signalling events
Gene Ontology:
Molecular function: amino acid binding; calcium ion binding; G protein-coupled receptor activity; protein binding; protein homodimerization activity; integrin binding; protein kinase binding; transmembrane transporter binding
Biological process: adenylate cyclase-inhibiting G protein-coupled receptor signaling pathway; detection of calcium ion; G protein-coupled receptor signaling pathway; intracellular calcium ion homeostasis; phospholipase C-activating G protein-coupled receptor signaling pathway; positive regulation of NLRP3 inflammasome complex assembly; anatomical structure morphogenesis; chemosensory behavior; ossification; regulation of calcium ion transport; bile acid secretion; branching morphogenesis of an epithelial tube; cellular response to glucose stimulus; cellular response to hepatocyte growth factor stimulus; cellular response to hypoxia; cellular response to low-density lipoprotein particle stimulus; cellular response to peptide; cellular response to vitamin D; chloride transmembrane transport; fat pad development; JNK cascade; positive regulation of calcium ion import; positive regulation of cell population proliferation; positive regulation of ERK1 and ERK2 cascade; positive regulation of insulin secretion; and 9 more
Cellular component: plasma membrane; apical plasma membrane; axon; axon terminus; basolateral plasma membrane; cell surface; glutamatergic synapse; membrane; neuronal cell body; presynaptic membrane
Genetic constraint (gnomAD): Loss-of-function variants: 24 observed, 71.97 expected, observed/expected ratio (o/e) 0.33, 90% interval 0.24 to 0.47. The upper end of that interval is the gene's LOEUF score, 0.47, which puts it in group 2 of 6, group 1 being the genes least tolerant of losing a copy. Missense variants: 922 observed, 1,421.5 expected, observed/expected ratio (o/e) 0.65, 90% interval 0.61 to 0.69. Synonymous variants: 538 observed, 575.62 expected, observed/expected ratio (o/e) 0.93, 90% interval 0.87 to 1.
Gene-disease validity (ClinGen):
ClinGen rates the evidence that CASR causes each of these diseases.
autosomal dominant hypocalcemia 1 (autosomal dominant): Definitive. Any autosomal dominant hypocalcemia in which the cause of the disease is a mutation in the CASR gene.
familial hypocalciuric hypercalcemia 1 (autosomal dominant): Definitive.
neonatal severe primary hyperparathyroidism (autosomal recessive): Definitive. Neonatal severe primary hyperparathyroidism (NSHPT) is characterized by severe hypercalcemia (> 3.5 mM) from birth and associated with major hyperparathyroidism.
epilepsy (autosomal dominant): Refuted. A brain disorder characterized by episodes of abnormally increased neuronal discharge resulting in transient episodes of sensory or motor neurological dysfunction, or psychic dysfunction.
Homologues: Orthologues: chimpanzee CASR (99% identical), macaque CASR (99% identical), pig CASR (94% identical), dog CASR (94% identical), mouse Casr (94% identical), rat Casr (94% identical), guinea pig CASR (90% identical), rabbit CASR (88% identical), tropical clawed frog casr (68% identical), zebrafish casr (66% identical). Paralogues in human: GPRC6A (27% identical), TAS1R2 (23% identical), TAS1R1 (22% identical), TAS1R3 (22% identical).
Diseases named in the same sentence as CASR in open-access papers:
CASR is named in the same sentence as 324 diseases in open-access papers, as found by Europe PMC text mining. Sharing a sentence is not in itself a finding about the gene and the disease. The quoted sentences say what the papers report.
Hypercalcemia (124 papers, 2008 to 2026). An abnormally increased calcium concentration in the blood. "In the neonatal period, the discovery of severe hypercalcemia accompanied by bone involvement should prompt suspicion of a genetic anomaly due to inactivating mutations of the CASR gene." (PMID 41568160, 2026). "In this syndrome, patients present with PTH-dependent hypercalcemia and relatively reduced calcium urinary excretion due to a germline variant in the calcium-sensing receptor (CaSR) gene or other CaSR-related genes (GNA11, AP2S1)." (PMID 39826015, 2025). "In normal physiology, PTH secretion is under tight control by the calcium-sensing receptor in a feedback system whereby hypocalcemia causes and hypercalcemia suppresses secretion of PTH." (PMID 41473615, 2025). "FHH1 is the most common form, accounting for ~ 65% of cases and, depending on the location and amino acid change in the CASR gene, determines the degree of loss of function and the severity of hypercalcemia." (PMID 38038882, 2024). "Familial hypocalciuric hypercalcemia type 1 (FHH-1) defines an autosomal dominant disease, related to mutations in the CASR gene, with mild hypercalcemia in most cases." (PMID 37602721, 2024). "The impaired signaling via the CaSR pathway in these disorders results in a higher set-point for the CaSR, which leads to hypercalcemia in association with plasma PTH concentrations that are in the normal reference range (~ 80%) or elevated." (PMID 38038882, 2024). "This is analogous to patients with inactivating mutations of the calcium sensing receptor, for whom life-long hypercalcemia also onsets in utero (as suggested by the animal model); they are unaccustomed to a “normal” serum calcium." (PMID 38577520, 2024). "In agreement with this, of the four CASR variant carriers we reported, one had severe hypercalcemia requiring hospitalization (ID15) and three had bone damage (osteoporosis)." (PMID 37810884, 2023). "Hypercalcemia due to neonatal severe HPT (NSHPT) secondary to homozygous or heterozygous mutations of CASR, has been treated since 2011 with cinacalcet, in association with biphosphonates, in order to avoid post-surgical hypoparathyroidism." (PMID 36090548, 2022). "Mutations in the CaSR gene result in resistance of the CaSR to extracellular calcium levels and diminished hypercalcaemia-induced calciuresis." (PMID 36536367, 2022). "Activating CASR mutations lead to hypercalcemia that reduces calcium and sodium transport in the Henle loop (Na-K-2Cl and paracellular pathways) through claudins, in association with a decreased urinary concentrating ability." (PMID 36090548, 2022). "There are over 200 known disease-associated mutations in CaSR that generally cause hypercalcemia, hyperparathyroidism, hypocalcemic hypercalciuria, and Bartter syndrome type V29,50,54,55." (PMID 35459864, 2022). "Despite not directly interacting with calcium, the variant was therefore considered highly likely to result in structural destabilisation of the calcium binding region and thus loss-of-function of CaSR, consistent with the hypercalcaemia phenotype." (PMID 35869530, 2022). "Inactivating CaSR variants are associated with hyperparathyroidism, hypercalcemia, and hypocalciuria with dominant (OMIM: 145980) and recessive (OMIM: 239200) modes of inheritance." (PMID 34772415, 2021). "Nevertheless, the complex associations between hypercalcemia, CaSR, and bone marrow hypocellularity needs further research." (PMID 34828498, 2021). "Although some studies have linked the development of hypercalcemia to CASR variants at these loci, direct evidence on the activity of the A986S and the Q1011E receptor variants remains to be clearly demonstrated." (PMID 34357109, 2021). "Rare inactivating CaSR variants classically cause hyperparathyroidism, hypercalcemia and hypocalciuria." (PMID 34772415, 2021). "The CASR allosteric activator cinacalcet has been reported to correct the hypercalcemia of patients with FHH2 due to GNA11 mutation." (PMID 33716975, 2021).
Hypercalcemia (continued). "In a preliminary diagnosis, it was concluded that the patient’s hypercalcemia was caused by an inactivating CaSR mutation based on the clinical lab results and sequence analysis of hypercalcemia-related genes." (PMID 35095753, 2021). "Although we also observed that these CASR SNPs were associated with several other disease phenotypes, including hypercalcemia and secondary malignancy of respiratory organs, these phenotypes did not pass the strict correction threshold." (PMID 34357109, 2021). "Familial hypocalciuric hypercalcemia type 1 (FHH1) is caused by loss-of-function mutations of the calcium-sensing receptor (CaSR) and is considered a benign condition associated with mild-to-moderate hypercalcemia." (PMID 32150253, 2020). "Familial hypocalciuric hypercalcemia (FHH) is a group of autosomal dominant disorders caused by dysfunction of the calcium sensing receptor (CaSR) and its downstream signaling proteins, leading to generally asymptomatic hypercalcemia." (PMID 32537548, 2020). "Heterozygous mutations of CaSR gene cause mild forms of asymptomatic hypercalcemia while homozygous mutations cause a rare form of NSHPT." (PMID 30376845, 2018). "For example, our associations between as CASR and hypercalcemia, GPT and alanine aminotransferease and UGT1A genes and bilirubin levels, were identified in all ways of filtering functionally annotated variation." (PMID 29545597, 2018). "Associations between CASR and hypercalcemia were least significant via the ‘all variants’ filtering category (functional annotation filter 1)." (PMID 29545597, 2018). "Adaptor protein-2 σ subunit (AP2σ) mutations impair CaSR internalization, leading to reduced sustained endosomal signaling and hypercalcemia in humans." (PMID 29420171, 2018). "Some cases of parathyroid adenomas, however, are associated with CASR gene mutations, thus justifying additional morphological investigations in case of severe hypercalcaemia, since excision of these adenomas can improve serum calcium levels." (PMID 28122587, 2017). "This is because patients with FHH have a loss of function or inactivating mutation in the gene for the calcium sensing receptor (CaSR), leading to hypercalcemia starting in fetal life." (PMID 27957351, 2016). "Both unaffected and heterozygous fetuses (with 1 inactivating mutation of the CaSR gene) are at risk for transient or permanent hypoparathyroidism due to suppression of their parathyroid glands in the setting of maternal hypercalcemia in pregnancy." (PMID 27957351, 2016). "In this report, we studied the functional consequences of a CaSR mutation identified in an infant with mild hypercalcemia, admitted in our Pediatric Department." (PMID 27087013, 2016). "An analysis of CaSR mutations identified in patients with PHPT or severe FHH that presented after infancy has indicated that CaSR mutations located in the receptor ECD are associated with more severe hypercalcaemia." (PMID 27647839, 2016). "In this study, we present the functional significance of a CaSR mutation identified in an infant with FHH who presented with asymptomatic hypercalcemia detected early in the infantile period." (PMID 27087013, 2016). "Cinacalcet has also been successfully used to manage life-threatening hypercalcaemia in NSHPT probands harbouring a heterozygous CaSR mutation, Arg185Gln." (PMID 27647839, 2016). "Patients with activating or inactivating germline mutations in the CASR present with hypocalcemia or hypercalcemia, respectively." (PMID 27803672, 2016). "This point mutation, inherited in heterozygosity and implicated in inactivating CaSR, leads to a loss of function of the receptor, with evidence, in the father, of hypercalcemia and unsuppressed PTH levels." (PMID 25292184, 2014). "Hypercalcemia causes a furosemide-like effect by inhibiting secretory potassium channel activity via actions initiated by the calcium-sensing receptor (CaSR) in the thick ascending limb of Henle’s loop." (PMID 24288027, 2013).
Hypercalcemia (continued). "Such a case has been reported previously of an infant born at 27 weeks gestation with moderate hypercalcemia and severe bone disease who was found to have an inactivating mutation (R220W) of CaSR." (PMID 22620673, 2012). "We report a case of unusually severe neonatal FHH due to a novel CaSR gene mutation that presented with perinatal fractures and moderate hypercalcemia." (PMID 22620673, 2012). "This is very different from neonatal severe hyperparathyroidism, due to biallelic mutations in the CASR gene, in which the hypercalcemia is fatal unless recognized early and subtotal parathyroidectomy is undertaken upon diagnosis." (PMID 21747852, 2011). "In the kidneys, mutations in CASR prevent the feedback inhibition of calcium reabsorption in situation of hypercalcemia, leading to relative hypocalciuria." (PMID 20727133, 2010). "Familial hypercalcemia with hypocalciuria is caused by autosomal dominant loss-of-function mutations in the gene encoding the calcium-sensing receptor (CASR), a G-protein coupled membrane receptor expressed in many tissues." (PMID 20727133, 2010). "For example, the mammalian CASR gene is known to be expressed in parathyroid glands and its loss in parathyroid gland in mice is implicated in hypercalcemia, hyperparathyroidism and growth retardation." (PMID 18452600, 2008). "Finally, the loss of sustained signaling by the PTH1R and CaSR have been associated with hypo- and hypercalcemia, respectively, further demonstrating the importance of such signaling in physiology." (PMID 39743506, 2025). "In addition, some genetic factors, such as calcium-sensing receptor polymorphisms, can predispose certain individuals to thiazide-induced hypercalcemia." (PMID 40911613, 2025). "These variants complete an allelic series of CASR by bridging the gap between common genome-wide association study (GWAS) variants and rare familial variants (a GoF causing hypocalcemia and a LoF causing hypercalcemia)." (PMID 40664210, 2025). "In conclusion, this paper reports the clinical and genetic characteristics of three Chinese females with heterozygous variants at different sites of the CaSR gene, accompanied by persistent hypercalcemia, hypocalciuria, and other diverse urinary biochemical abnormalities." (PMID 40417236, 2025). "Familial hypocalciuric hypercalcemia type I (FHH1) is caused by heterozygous loss-of-function mutations in the CaSR gene, and is characterized by the combination of hypercalcemia, hypocalciuria, normal to elevated PTH, and facultatively hypermagnesemia and mild bone mineralization defects." (PMID 38386045, 2024). "Further research is needed to determine whether factors such as calcium-sensing receptor mutations contribute to hypercalcemia in adrenal insufficiency." (PMID 39712788, 2024). "Moreover, we found a pathogenic variant (p.Arg648*) in the CASR gene in another patient (index case CA0109) who had hypercalcemia but with hypercalciuria." (PMID 38586466, 2024). "Our data suggest that expression of CaSR variants at rs1801725 is associated with a higher risk of developing secondary neoplastic lesions in the lungs and bone, due in part to cancer-induced hypercalcemia and/or tumor immune suppression." (PMID 34357109, 2021). "Our data suggest that the CaSR variant at rs1801725, is associated with a higher risk of developing secondary neoplastic lesions in the lungs and bone due in part to cancer-induced hypercalcemia and/or tumor immune suppression." (PMID 34357109, 2021). "Overall, results confirm that CaSR nonsense/frameshift variants promote hypercalcemia." (PMID 32386559, 2020). "Thus, children of a mother with FHH1 can develop hypercalcemia or transient neonatal hypocalcemia, depending on the underlying inherited CaSR mutation, and require investigations for serum calcium and CaSR mutations in early childhood." (PMID 32150253, 2020).